CRYBA1 (crystallin beta A1)
Description:
Crystallins are the dominant structural components of the vertebrate eye lens.
Synonyms: CRYB1; CTRCT10
Tractability: No criterion of Open Targets' tractability assessment is met for any kind of drug.
Gene: Protein-coding gene on chromosome 17 (29,246,859 to 29,254,494, forward strand). Ensembl gene ENSG00000108255.
Gene Ontology:
Molecular function: protein binding; structural constituent of eye lens
Biological process: lens development in camera-type eye; visual perception; negative regulation of cytokine production; negative regulation of ERK1 and ERK2 cascade; negative regulation of phosphatidylinositol 3-kinase/protein kinase B signal transduction; negative regulation of TOR signaling; phagocytosis; positive regulation of anoikis; regulation of autophagy
Genetic constraint (gnomAD): Loss-of-function variants: 20 observed, 29.45 expected, observed/expected ratio (o/e) 0.68, 90% interval 0.48 to 0.99. The upper end of that interval is the gene's LOEUF score, 0.99, which puts it in group 4 of 6, group 1 being the genes least tolerant of losing a copy. Missense variants: 178 observed, 227.86 expected, observed/expected ratio (o/e) 0.78, 90% interval 0.69 to 0.88. Synonymous variants: 84 observed, 71.63 expected, observed/expected ratio (o/e) 1.17, 90% interval 0.98 to 1.41.
Homologues: Orthologues: chimpanzee CRYBA1 (99% identical), macaque CRYBA1 (97% identical), dog CRYBA1 (96% identical), guinea pig CRYBA1 (95% identical), mouse Cryba1 (95% identical), rat Cryba1 (95% identical), rabbit CRYBA1 (94% identical), pig CRYBA1 (92% identical), tropical clawed frog cryba1 (76% identical), zebrafish cryba1a (74% identical). Paralogues in human: CRYBA4 (60% identical), CRYBA2 (48% identical), CRYBB1 (44% identical), CRYBB3 (40% identical), CRYBB2 (40% identical), CRYBG1 (32% identical), CRYBG3 (31% identical), CRYBG2 (30% identical), CRYGS (29% identical), CRYGC (28% identical), CRYGB (27% identical), CRYGA (26% identical), and 2 more.
Diseases named in the same sentence as CRYBA1 in open-access papers:
CRYBA1 is named in the same sentence as 26 diseases in open-access papers, as found by Europe PMC text mining. Sharing a sentence is not in itself a finding about the gene and the disease. The quoted sentences say what the papers report.
cataract (9 papers, 2011 to 2024). Partial or complete opacity of the crystalline lens of one or both eyes that decreases visual acuity and eventually results in blindness. "Overall, our examination of patients with hereditary cataracts detected a single pathogenic variant, c.272_274delGAG (p.G91del), in the CRYBA1 gene, with a frequency of 2.2% in the total sample of patients and 3% among patients with autosomal dominant cataract." (PMID 37367076, 2023). "In this study, we investigated genetic variants in CRYAA, CRYAB, CRYGC, CRYGD, CRYBA1, GJA8, and GJA3 genes in 94 patients with congenital isolated cataracts from 45 unrelated families." (PMID 37367076, 2023). "To investigate the expression levels of CRYBA1 in cataract patients and normal controls, we collected capsule pieces from the cataract surgeries and the eye bank and used them for quantification studies." (PMID 31488069, 2019). "The mRNA and protein levels of CRYBA1 in the lens epithelium from cataract patients and normal controls were compared using quantitative polymerase chain reaction (qPCR) and Western blot analyses." (PMID 31488069, 2019). "For the lens, which is largely made up of crystallins, we find many crystallin genes (Crybb3, Cryba1, Crybb1, Crygc, Crygs, etc.)in our accelerated set of genes contributing to various forms of cataracts." (PMID 29035697, 2017). "The expression levels of Cryga and Cryba1 in the cataract model group were up-regulated." (PMID 36678523, 2022).
congenital cataracts (5 papers, 2011 to 2023). "This mutation supports the role of the CRYBA1/A3 gene in human cataract formation and provides more evidence of genetic heterogeneity of congenital cataracts." (PMID 21850182, 2011). "An in-frame one amino acid deletion in the beta-crystalline gene CRYBA1 has been reported in several different Chinese, Caucasian and Iranian families of congenital cataracts." (PMID 31488069, 2019). "The crystallin (CRYAA, CRYAB, CRYGC, CRYGD, and CRYBA1) and connexin (GJA8, GJA3) genes were analyzed in 45 unrelated families from the Volga–Ural Region (VUR) with hereditary congenital cataracts." (PMID 37367076, 2023). "A subset of the 7-days radiation only DEG (Cryaa, Cryba1, Cryba2, Cryba4, Crybb1, Crybb2, Crybb3, Crygs, Bsfp1) were enriched in nuclear and congenital cataracts, however, these genes were not dysregulated at 1 month or 4 months." (PMID 36207342, 2022).
Nystagmus (3 papers, 2017 to 2019). Rhythmic, involuntary oscillations of one or both eyes related to abnormality in fixation, conjugate gaze, or vestibular mechanisms. "In this study, we used WES to identify mutations among the five members of a two-generation Chinses family with CC, esotropia and nystagmus and found that the CRYBA1 mutation (c." (PMID 31488069, 2019).
age-related macular degeneration (2 papers, 2019 to 2021). Age-related loss of vision in the central portion of the retina (macula), secondary to retinal degeneration. "al correlated the increase in RPE Lipocalin-2 levels with chronic inflammatory conditions, in Cryba1 cKO mice simulating age-related macular degeneration (AMD)." (PMID 31891637, 2019).
autosomal dominant cataract (2 papers, 2017 to 2023). A syndromic cataract that has autosomal dominant inheritance. "The novel deletion mutation (c.271_273delGAG) in exon 4 of CRYBA1 was identified in a family with autosomal dominant congenital cataracts." (PMID 28450710, 2017).
diabetes (2 papers, 2018 to 2021). "From our RNA sequencing analysis, it emerges that diabetes and the metabolic syndrome induce the expression of crystallin β (i.e. Crybb3, Cryba2, Cryba1) and γ (i.e. Crygc, Crygb, Crygf) in the retina, whereas we did not observe any significant effect on α crystallins." (PMID 30093686, 2018). "However, Crybb3, Cryba2, Crygc, Crygb, Crygf, Cryba1 were only upregulated in obese 42, indicating that their expression was likely affected by diabetes and metabolic diseases." (PMID 30093686, 2018).
geographic atrophy (1 paper, 2023). "Similarly, in geographic atrophy patients and the conditional Cryba1 knockout mouse model of geographic atrophy, neutrophils infiltrate the retina and are associated with chronic inflammation." (PMID 37626902, 2023). "It has been demonstrated that RPE cells stimulate neutrophil activation and infiltration into the retina in a geographic atrophy mouse model with a knockout of Cryba1 gene in RPE." (PMID 37626902, 2023).
myopia (1 paper, 2017). "There was no myopia or history of retinal detachment, suggesting the variant in CRYBA1 was causative of the phenotype." (PMID 28378818, 2017).
retinal degeneration (1 paper, 2022). Degeneration of the retina. "We also observed a decrease in CD11b on microglia in aged Cryba1 cKO, a change previously shown to be important for pathogenic accumulation of these immune cells in the SRS leading to chronic inflammation and retinal degeneration." (PMID 36428965, 2022).
retinal ischemia (1 paper, 2007). A ischemic disease that involves the retina. "A microarray study on retinal ischemia reported an upregulation of Cryaa, Cryab, Cryba1/3, Crybb2, Crygc, and Grifin transcript levels after 12 h of reperfusion, but no qPCR validation was presented." (PMID 17327827, 2007).
uveitis (1 paper, 2012). An inflammatory process affecting a part of or the entire uvea. "Crystallins that belong to the small heat shock protein family have a non-structural role, and retina-specific elevated levels of Cryaa, Cryba1, Crygs, Crybb2, Crygb, and Crygc have been reported in experimental uveitis." (PMID 22605924, 2012).
cancer (4 papers, 2020 to 2024). A tumor composed of atypical neoplastic, often pleomorphic cells that invade other tissues. "We used a dual-probe evaluation and considering the combined signals of HER2 (a red signal) and CRYBA1 (a green signal), 2 (2/16; 12.5%) carcinomas were amplified, and 14 (14/16; 87.5%) carcinomas were not amplified." (PMID 39335216, 2024). "A morphological translocation-fusion pattern was recognized in 20 carcinomas (22%), with a co-localized signal of HER2 and CRYBA1." (PMID 36356060, 2022). "High expression of ITGB1, CAV1 and low expression of CRYBA1, CEACAM5 were observed in all, suggesting the lack of anchorage-independent growth of the two cancer-derived cells is due to different mechanisms than lack of anoikis resistance." (PMID 37264224, 2023).
infection (2 papers, 2021). The state of being infected such as from the introduction of a foreign agent such as serum, vaccine, antigenic substance or organism. "The downregulation of Cryba1 in these cells upon infection with lentiviral shRNA was confirmed by qPCR." (PMID 33627831, 2021). "Infection efficiency was similar for control and Cryba1 cKO RPE flatmounts." (PMID 34239035, 2021).
benign neoplasm (1 paper, 2022). A neoplasm which is characterized by the absence of morphologic features associated with malignancy (severe cytologic atypia, tumor cell necrosis, and high mitotic rate). "Epithelial cells of the normal mammary glands, lobular hyperplasia, and benign neoplasms showed diploid HER2 and CRYBA1 signals." (PMID 36356060, 2022).
eye disorder (1 paper, 2019). A non-neoplastic or neoplastic disorder that affects the eye. "We performed molecular experiments to confirm that the p.G91del mutation in CRYBA1 results in abnormal expression and distribution of CRYBA1 protein, and this study could serve as an example of the pathogenicity of an in-frame small deletion in an inherited eye disorder." (PMID 31488069, 2019).
CRYBA1 also shares sentences with these, for which no sentence is quoted: breast carcinoma (1 paper); Esotropia (1); macular degeneration (1); metabolic disease (1); metabolic syndrome (1); microphthalmia (1); night blindness (1); nuclear cataract (1); ptosis (1); retinal detachment (1); retinitis pigmentosa (1).